SPP1 (secreted phosphoprotein 1)
Diseases named in the same sentence as SPP1 in open-access papers (continued):
Sharing a sentence is not in itself a finding about the gene and the disease.
tumor (continued). "COL11A1+ CAFs co-localise with SPP1+ macrophages at tumour borders and their interaction promotes the production of collagen by CAFs, that obstacles the contacts between tumour cells and cytotoxic immune cells, leading to immune exclusion." (PMID 40849356, 2025). "Compared with PD-L1, a canonical immune checkpoint molecule mainly expressed on tumor and immune cells that directly inhibits effector T cell activity, SPP1 functions as an upstream or indirect immune suppressor." (PMID 41391064, 2025). "Secreted phosphoprotein 1 (SPP1) is a secreted glycoprotein that widely expresses in tumour tissues and participates in tumour biological functions, including tumour cell proliferation, cell invasion and drug resistance." (PMID 40495644, 2025). "With its potential role in driving collagen deposition and organization, SPP1 regulates various pathological events associated with extracellular matrix (ECM) remodeling, including calcification, tumor progression and fibrosis." (PMID 41477484, 2025). "Using IFN-γ drugs to increase IFN-γ concentration in the body is a viable method to enhance the anti-tumor immune response and inhibit SPP1 expression." (PMID 41391064, 2025). "While SPP1+ TAMs are known to promote tumor progression through immunosuppressive mechanisms, the SPP1+BCL2A1+ TAM subset further exhibits a distinct transcriptional program associated with resistance to cell death." (PMID 41225975, 2025). "Targeting SPP1 in macrophages enhanced RT efficacy, reduced tumor burden, and restored antitumor immunity." (PMID 41221295, 2025). "Our data suggest that C1 cells actively recruit SPP1+ macrophages into the tumor and polarize them toward an M2-like phenotype." (PMID 41374989, 2025). "Accordingly, blocking TGF-β signaling to prevent myCAF differentiation, targeting SPP1 to disrupt CAF–tumor cell crosstalk, or inhibiting downstream ERK/MAPK signaling can restore sensitivity to ADT." (PMID 41514658, 2025). "High expression of ASPH significantly enhances the VISFATIN signaling pathway among epithelial, fibroblast, myeloid cell and macrophage and SPP1 signaling pathway among epithelial, fibroblast and macrophage in the tumor microenvironment of gallbladder." (PMID 40110547, 2025). "The extensive crosstalk between TAMs and stromal and/or tumor cells by SPP1 and its receptors underscores their importance." (PMID 39920772, 2025). "Pathway analysis of the differential ligand–receptor interactions between tumor and normal environments highlighted SPP1 as a significantly upregulated signaling factor in tumors." (PMID 41268553, 2025). "Tumor-derived extracellular vesicles (TEVs) enriched with Circ-0034880 promote strong interactions between primary tumor cells and SPP1 high CD206 tumor-promoting macrophages, fostering PMN formation and CRLM." (PMID 40034694, 2025). "SPP1 derived from tumor and immune cells activates CAFs via the CD44 signaling pathways, enhancing the secretion of collagen (COL1A1, COL1A2) and fibronectin (FN1)." (PMID 41391064, 2025). "CXCL9/10/11 levels were markedly lower than SPP1, consistent with the downregulation of these three chemokines by tumor cell-secreted factor(s) in short-term stimulation of control monocytes." (PMID 40176808, 2025). "Specifically, we revealed that the less‐SPP1+ Mph and APOE+ Mph cells in patients with low EDEM3‐expressed tumours was associated with the best response." (PMID 39754316, 2025). "Mechanistically, it is demonstrated that PLIN2 boosts HIF1α/SPP1 signaling in macrophages, thereby exerting pro‐tumor functions." (PMID 39921309, 2025). "Comparative analyses revealed a marked enrichment of SPP1+ TAMs in tumor tissues relative to normal liver (p < 0.0001)." (PMID 41225975, 2025). "Tumor samples were histologically accessed in order to gain insights into the distribution of SPP1+ macrophages in our cohort." (PMID 40666097, 2025).
tumor (continued). "Our findings revealed that the infiltration of SPP1+ TAMs was markedly elevated in tumor tissues relative to normal tissues, and the proportion of SPP1+ TAMs increased with the advancement of tumor stage." (PMID 40230843, 2025). "In cancer research, SPP1 has been shown to respond to matrix stiffness, with higher levels observed in stiffened tumor regions compared to adjacent tissues." (PMID 41477484, 2025). "In adjacent non‐tumor tissue, SPP1+ TAMs exhibit an M1 phenotype, while in tumor tissue, particularly in PHT, SPP1+ TAMs exhibit an M2 phenotype, displaying stronger immunosuppressive features." (PMID 41028931, 2025). "Distinct ligand–receptor communications were observed between high- and low-pyroptosis groups, among which the SPP1-centered signaling axis showed pronounced remodeling, suggesting a pivotal role in tumor–immune crosstalk." (PMID 41208987, 2025). "integrated ST with scRNA-seq and multi-immunofluorescence to identify a tumor immune barrier (TIB) composed of SPP1+ macrophages and CAFs at the tumor boundary." (PMID 40264779, 2025). "One study demonstrated that the knockout of SPP1 significantly inhibited the infiltration of M2 TAMs in xenograft tumors, while RNA aptamer-based blockade of SPP1 markedly suppressed tumor growth and M2 TAM infiltration in mouse models." (PMID 40191203, 2025). "Our analysis identified specific signaling pathways, including MIF and SPP1 signaling in subtype 1, which were noted for their implications in tumor progression and immunosuppression." (PMID 40761262, 2025). "One study indicated that, at the forefront of tumor invasion, two populations of tumor cells co-localized more frequently with SPP1+ macrophages than with other cell types." (PMID 40191203, 2025). "Previous studies have established correlations between elevated levels of circulating SPP1 or increased expression of SPP1 on tumor cells and poor prognosis in many types of cancer." (PMID 41282023, 2025). "The suppression of T cells leads to a deficiency in activating signals such as IFN-γ, thereby permitting macrophages to adopt an alternative, pro-tumoral (M2-like/SPP1+) activation state under the influence of tumor-derived factors." (PMID 41425545, 2025). "Within the immune system, SPP1 is highly expressed by activated macrophages, where it contributes to shaping the tumor immune microenvironment as a tumour-immune barrier structure by promoting T-cell exhaustion and suppressing cytotoxic activity." (PMID 41225975, 2025). "Regarding tumor cells, the SPP1/CD44 axis is crucial for communication between tumor cells and TAMs." (PMID 41391064, 2025). "Macrophages and OS cells emerged as dominant sources of multiple tumor-relevant signals, including SPP1, TNF, MIF, GALECTIN, ANNEXIN, and VEGF." (PMID 40895569, 2025). "The functional overlap of SPP1+ macrophages across cancer types highlights their potential as universal mediators of tumor progression and therapeutic resistance." (PMID 40047497, 2025). "We provide strong evidence that the designed synthetic 7aaRGD peptide, which targets SPP1/integrin-mediated signaling and has been previously validated in in vitro experiments, blocks tumor-induced reprogramming of myeloid cells in vivo." (PMID 40281508, 2025). "Collectively, these findings underscore the pivotal role of SPP1 in orchestrating a tumor-promoting immune milieu, highlighting its potential as a therapeutic target in cancer immunotherapy." (PMID 41391064, 2025). "Consistently, previous studies have found that the interaction between SPP1+ TAMs and fibroblasts contributes to the formation of a tumor immune barrier, promotes the accumulation of ECM structures, and is important for the efficacy of immunotherapy." (PMID 40230843, 2025). "According to our findings, SPP1+BCL2A1+ TAMs were consistently enriched in tumor tissues compared with adjacent normal liver, and their abundance strongly correlated with poor response to PD-1 blockade." (PMID 41225975, 2025).
tumor (continued). "Overall, SPP1 is an important extracellular matrix protein involved in biological processes such as skeletal development, immune regulation, and tumor progression." (PMID 40196737, 2025). "Conversely, knockdown of MIF leads to anti-tumor effects of myeloid cells, which attributes to the reduction of SPP1+ macrophages that play roles in extracellular matrix remodeling." (PMID 39891284, 2025). "In agreement with the protein expression data, mRNA levels of the the genes CHI3L1 and SPP1 were also higher in tumor samples than in controls." (PMID 40703808, 2025). "As shown by integrating scRNA‐seq and ST‐seq data, macrophages were enriched in spots surrounding tumour cells, validated by the expression of SPP1." (PMID 39934971, 2025). "This alteration was accompanied by an upregulation of the tumor-associated FASLG signaling pathway and a concomitant downregulation of the tumor-promoting SPP1 pathway." (PMID 40725216, 2025). "Of note, SPP1 positive myeloid cells are known to be anti-inflammatory and pro-tumor in multiple cancers." (PMID 40883281, 2025). "In general, all four types of cancer studied showed an activation of SPP1 as well as some of its highly correlated oncogenes; that is, its interacting partners co-involved in tumor progression." (PMID 39857756, 2025). "This change also reshapes the tumor’s surroundings, creating an environment that suppresses the immune system, largely by recruiting and activating specific immune cells called SPP1+ macrophages." (PMID 41374989, 2025). "This table summarizes the role of SPP1 in various tumor types based on findings from clinical studies, in vitro and in vivo experiments, and bioinformatics analyses." (PMID 41391064, 2025). "Prior studies have demonstrated a strong positive correlation between SPP1 expression and the infiltration of diverse immune cell subsets in cancer, implicating it in the establishment of an immunosuppressive tumor microenvironment." (PMID 41221294, 2025). "The tumor group exhibited statistically significant differences in SPP1, LYZ, and MCM5 expression levels in NK/T cells, myeloid cells, epithelial cells, and other cells compared to the healthy control group." (PMID 41384115, 2025). "Further in vitro experiments showed that targeting the SPP1-CD44 axis restored T cell function, and anti-SPP1 treatment significantly reduced tumor burden, either alone or in combination with anti-PD1 therapy in mouse models." (PMID 40883281, 2025). "Tumor area activated various proliferation and metastasis-related signaling pathways (MK, SPP1, SEMA3, MIF, VEGF, PERIOSTIN, and PDGF) and immunosuppression-related signaling pathway (GALECTIN)." (PMID 39670859, 2025). "SPP1+ macrophages interacted with CAFs, forming a tumor immune barrier restricting immune cell infiltration into the tumor core, thus confining anti-PD-1 therapy in HCC mice." (PMID 40416872, 2025). "AR-imprinted TREM2/SPP1 TAMs cluster near tumor nests, CAFs, and vasculature; specifically enriched in the bone metastatic niche." (PMID 41488638, 2025). "In tumor-promoting settings, SPP1 interacts with its receptors—primarily integrins and CD44—to activate multiple downstream signaling cascades that facilitate cancer cell migration, invasion, and metastatic spread." (PMID 41391064, 2025). "To further investigate the relationship between the SPP1+ TAMs and tumor progression, we employed the deconvolution algorithm to infer the cell proportion for each sample from the bulk RNA-seq data." (PMID 40230843, 2025). "Prior studies have demonstrated that SPP1 interacts with CD44 to promote tumour cell proliferation and metastasis, while FN1, through integrin‐mediated adhesion signalling, enhances cell survival and invasion and drives metastatic progression." (PMID 40988131, 2025).
tumor (continued). "We found mice treated with anti-VSIG4 or anti-SPP1 antibody alone exhibited slower tumor growth, and combination therapy with VSIG4 and SPP1 blockade synergistically enhanced anti-tumor activity without affecting body weight." (PMID 39920772, 2025). "Impaired DC activity reduces the activation of anti-tumor T cells, indirectly facilitating the persistence and polarization of SPP1+ TAMs." (PMID 41425545, 2025). "It is shown that the lead compound (CANDI460) can down‐regulate SPP1 in vitro and in vivo and lead to tumor remissions in different murine models." (PMID 39639496, 2025). "SPIC and MAFB were predominantly expressed in normal and adjacent tissues, while SPP1+ TAM-associated TFs (SREBF1, JUN, SPI1, and CREB1) showed peak expression in tumor core regions." (PMID 40725473, 2025). "Using SOAR, we found that CXCL16/SPP1 macrophage polarity characterizes the coordination of immune cell polarity in the tumor microenvironment." (PMID 40498826, 2025). "Meanwhile, ZEB1 blockade attenuates CD44+ neutrophil–induced CD8+ T cell exhaustion by reducing tumor-derived SPP1 secretion, which otherwise promotes exhaustion through activation of the PD-L1/PD-1 pathway." (PMID 40924501, 2025). "In RTTPtgs1/2 KO tumours, we observed an increase in both monocytes and inflammatory monocytes, with a reduction in immunosuppressive TAMs (Spp1+, C1q+ and Ctsk+) and an increase in H2-Ab1 TAMs." (PMID 39604727, 2025). "For example, two distinct tumor-associated macrophages (TAMs) populations, namely C1QC+ and SPP1+ TAMs, with only the latter being specifically enriched in CRC have been identified." (PMID 41316282, 2025). "The resulting SPP1+ myCAFs express and secrete high levels of SPP1, which engages integrin receptors on tumor cells and activates the ERK/MAPK pathway, thereby increasing resistance to antiandrogen therapies (e.g., enzalutamide, ENZ)." (PMID 41514658, 2025). "Given the clinical importance of the SPP1+ TAMs, we further explored their functional plasticity within the tumor microenvironment." (PMID 40725473, 2025). "These spatial and prognostic patterns align with previous reports implicating CXCL9 as a marker of immunoactive macrophages and SPP1 as a regulator of tumor progression and immune evasion." (PMID 40725473, 2025). "These SPP1+ TAMs are enriched in tumor tissues compared to normal liver, and their abundance has been associated with poor overall survival." (PMID 41225975, 2025). "Collectively, these findings suggest that SPP1+ TAMs exacerbate hypoxia and drive tumor progression in high PIVKA‐II expression tumors." (PMID 41028931, 2025). "Comparative boxplot analyses confirmed significantly elevated SPP1+BCL2A1+ TAM scores in tumor versus normal tissues (p < 0.05)." (PMID 41225975, 2025). "We observed that in advanced-stage LUAD, the proportions of both eCAFs and SPP1+ macrophages increased with the progression of tumor." (PMID 40657391, 2025). "The spatial co-localization of KLK6-positive cells with SELENOP+ and SPP1+ macrophages is also particularly noteworthy, as these subsets are known to exhibit immunosuppressive properties and promote tumor angiogenesis." (PMID 41383634, 2025). "Communication analysis demonstrated strong interactions between SPP1+ IR macrophages and T cells, particularly in tumor tissues, with the SPP1–CD44 axis showing the strongest interaction." (PMID 41221295, 2025). "Cell communication analysis suggested that SPP1 secretion by tumor cells binds to CD44 on neoplastic stem cells, activating the PI3K/AKT pathway and enhancing lncRNA transcription." (PMID 40076844, 2025). "For instance, COL3A1 plays a role in ECM stiffness and tumor invasion in both squamous and adenocarcinoma types, and PLAU and SPP1 have been implicated in promoting tumor cell migration and metastasis via interactions with integrins and the PI3K/AKT pathway." (PMID 41465316, 2025).
tumor (continued). "SPP1+ TAMs have recently been identified as an emerging subset involved in T cell suppression, tumor progression, and drug resistance." (PMID 39920772, 2025). "Co-culture experiments with THP-1-derived macrophages, followed by Western blot, flow cytometry, and functional assays, were performed to investigate SPP1-mediated macrophage polarization and its impact on tumor progression." (PMID 40303328, 2025). "Combining SPP1-targeted approaches with immunotherapy such as anti-PD-1/PD-L1 agents can alleviate immunosuppressive barriers, enabling effective T cell-mediated tumor attack." (PMID 41425545, 2025). "In particular, SPP1 (osteopontin)-expressing macrophages were enriched in the tumor core and inhibited T cell infiltration." (PMID 40647561, 2025). "On the contrary, M2-type TAMs suppress T cell-mediated anti-tumor immunity through multiple signaling pathways, including the CD86/cytotoxic T-lymphocyte associated protein 4 (CTLA4) and secreted phosphoprotein 1 (SPP1)/CD44 pathways." (PMID 40600065, 2025). "Significant communications were observed between tumor cells and immune cells through three signaling pathways: SPP1, MIF, and APP." (PMID 39584073, 2025). "By bridging chronic inflammation and immune regulation, SPP1 connects metabolic disorders such as T2D to cancer progression, facilitating tumor survival and metastasis." (PMID 40127075, 2025). "The interaction between LEMS and SPP1+ macrophages creates a pro‐metastatic niche that facilitates tumor cell migration and invasion." (PMID 41176774, 2025). "Differential gene expression analysis also revealed that SPP1 was downregulated in tumor-infiltrating macrophages after GCP treatment." (PMID 41409288, 2025). "Elevated JNK activity, linked to poor breast cancer outcomes, promotes tumor growth and metastasis by upregulating ECM components SPP1 and TNC, which are c-Jun targets." (PMID 40342734, 2025). "SPP1 expression was significantly greater in HNSCC tumor samples than in normal oral epithelial tissue samples." (PMID 39726047, 2024). "More notably, SPP1 has been demonstrated to be involved in immune regulation, cell survival, and tumor progression." (PMID 38612943, 2024). "This article consolidates the significance and prospects of CXCL9:SPP1 as a novel indicator for tumor development and prognosis, while also proposing future research directions and addressing potential challenges in this promising field." (PMID 38217023, 2024). "Recent studies have highlighted the pivotal roles of SPP1, ANGPT2, and NCL in regulating the polarization of tumor-associated macrophages (TAMs), offering a new perspective on their potential as targets for cancer therapy." (PMID 38806553, 2024). "Thereby, our findings underscore a bidirectional EGC-TAM interaction which was proven to influence tumor burden and SPP1+ TAMs in three independent CRC mouse models." (PMID 39030280, 2024). "The proximity relationship between SPP1+ macrophages and proliferating tumor cells has also been confirmed by mIHC technology." (PMID 39716897, 2024). "SPP1 + macrophages are among the major phagocytic cells, yet promoting tumor immune evasion and predicting unfavorable prognosis, in various cancer types." (PMID 39696410, 2024). "We found that in metastatic PDAC tumours, MAFs and cancer cells express high levels of Spp1, and that STAT3i reduces Spp1 expression in both cell types." (PMID 38678021, 2024). "The results showed that inhibiting macrophage-derived TNF-α and IL-1β decreased the growth of tumor cells and SPP1-NC also exhibited the secretion of TNF-α and IL-1β." (PMID 39726047, 2024). "SPP1 + macrophages were reported to be enriched in hypoxic and necrotic tumor regions serving as phagocytic cells for phagocytosing dying cells." (PMID 39696410, 2024).